STAT3 (signal transducer and activator of transcription 3)
Diseases named in the same sentence as STAT3 in open-access papers (continued):
Sharing a sentence is not in itself a finding about the gene and the disease.
cancer (continued). "Considering the evidence that STAT3 is involved in the proliferation of cancer-initiating cells as well as cancer cells, we set out to investigate whether metformin impaired cell proliferation in precursor lesions." (PMID 28738823, 2017). "Previously, the importance of direct contact was the focus of investigations regarding cell–cell interactions; for example, STAT3 activation in several types of cancer cells has been identified to be significantly induced by the direct coculture of macrophages and cancer cells." (PMID 28157698, 2017). "Increasing evidence indicates that signal transducer and activator of transcription 3 (STAT3) and mitogen-activated protein kinase (MAPK) signaling pathways are closely associated with inflammatory processes and play major roles in inflammation and cancer." (PMID 29245934, 2017). "Furthermore, transcriptional programs regulated by STAT3 (Signal transducer and activator of transcription 3) and YAP (Yes associated protein 1) within cancer-associated fibroblasts have been shown to support collective migration of cancer cells." (PMID 28715714, 2017). "STAT3 suppression when combined with PTEN inactivation might therefore accelerate cancer progression." (PMID 28102325, 2017). "Recent studies showed that the STAT3 pathway mediated radioresistance in many malignant tumors." (PMID 29226125, 2017). "Crytotanshinone (CPT) showed potential therapeutic value in animal breast model through enhancing cytotoxic CD4+ T cells by up-regulating JAK2 and STAT4 phosphorylation, suggesting that STAT4 may be play opposite function with STAT3 in human cancers." (PMID 28422733, 2017). "Therefore, TTB suppresses cancer progression by promoting ROS-mediated inhibition of STAT3 signaling, suggesting that TTB is useful for the treatment of cancer." (PMID 28245605, 2017). "STAT3 is considered as an important factor in inflammation and cancer development." (PMID 28903349, 2017). "In tumors, constitutively active STAT3 drives cell proliferation through upregulation of cell cycle-regulators such as c-Myc and Cyclin D, promotes pluripotency of cancer stem cells, and potentiates metastasis by modulating cytoskeleton and extracellular matrix." (PMID 28222105, 2017). "Furthermore, icaritin suppressed the expression of p-JAK2 and p-STAT3 in mice carcinoma tissue, which was consistent with our results in vitro." (PMID 28085115, 2017). "Besides, STAT3 is a promising target for the development of clinical therapeutic agents for carcinoma chemoprevention." (PMID 29242509, 2017). "Addition of STAT3 inhibitors to radiation therapy increased clearance of cancer xenografts in mice." (PMID 27027445, 2016). "Developing drugs that can effectively block STAT3 activation may serve as one of the most promising strategy for cancer treatment." (PMID 26784960, 2016). "Furthermore, IL-11 induced STAT3 phosphorylation and increased anti-apoptotic protein Bcl-2 and Survivin expression in cancer cells." (PMID 27922075, 2016). "In cancer, Stat3 contributes to proliferation, apoptosis, and angiogenesis." (PMID 27589562, 2016). "Caution should therefore be used when treating TSC and related cancers by targeting STAT3." (PMID 27078846, 2016). "Although the cross-talking between STAT3 and NF-κB can further promote cancer cell proliferation and survival, it is unknown whether co-regulation of STAT3 and NF-κB plays an important role in CLL cell survival and disease progression." (PMID 27074565, 2016). "Targeting this domain may prove more successful in abrogating STAT3 activity in cancer, as these compounds have the potential to inhibit STAT3 transcriptional activity regardless of dimerization status." (PMID 27793003, 2016). "Furthermore, it was also observed that IL-11 induced STAT3 phosphorylation and increased anti-apoptotic protein Bcl-2 and Survivin expression in cancer cells." (PMID 27922075, 2016).
cancer (continued). "Since dysregulation of STAT3 is detected in many human cancers including KSHV-infected PEL and KS tumors, we asked whether STAT3 signaling was involved in miR-K6-3p induction of endothelial cell migration and angiogenesis." (PMID 27128969, 2016). "Since STAT3 signaling has central roles in CSCs, our above effective combination treatment might be resulted from both eliminating the proliferating cancer cells by radiation and eradicating CSCs by Lip-FLLL32." (PMID 26887043, 2016). "Consequently, cancer cell growth was significantly reduced and STAT3-activation was inhibited by ONA." (PMID 27404320, 2016). "The S1P/S1PR1/STAT3 axis controls the development of several cancer type." (PMID 28039439, 2016). "Collectively, our data support the notion that activation of the IL-6/STAT3 and inflammatory-like signaling leads to deleterious effects in normal prostate epithelial cells and tumors, leading to expansion of the cancer stem-like cell compartment and self-renewal properties." (PMID 27732936, 2016). "Thus, there is substantial evidence for aberrant activation or increased levels of STAT3 in gammaherpesvirus-related cancers and cancer models." (PMID 27458446, 2016). "It should be noted that, in contrast to STAT1/2/5 proteins, constitutive and IL-6-induced STAT3 phosphorylation was shown to be reduced upon treatment by SFN in a number of cancer cell lines, thus revealing multiple modes of regulation of STAT proteins by ITCs." (PMID 27304884, 2016). "The STAT3 signaling pathway is a representative oncogenic pathway in cancer." (PMID 26824417, 2016). "STAT3 activation in cancer cells results in enhanced cell proliferation and survival." (PMID 31051015, 2016). "Stat3 has been identified with critical importance for maintaining cancer stemness." (PMID 27460364, 2016). "Therefore, STAT3 can be designed as a target for overcoming MDR of cancer cells induced by HDACIs in clinical cancer therapy." (PMID 27409663, 2016). "Besides, direct co-culture with M2 macrophages was observed to be able to pronouncedly activate STAT3 signaling pathway in cancer cells, contributing to the proliferation and progression in cancers." (PMID 27765933, 2016). "IR is known to activate Akt and Stat3 signaling pathways resulting in radio-resistance in cancer." (PMID 27895317, 2016). "STAT3 is well demonstrated to play a crucial role in tumorigenesis and cancer-related inflammation." (PMID 27835881, 2016). "Aberrations in a specific STAT3 regulator such as the protein inhibitor of activated STAT3 (PIAS3) may also contribute to cancer development." (PMID 26768588, 2016). "STAT3 signaling is often persistently activated in cancer cells." (PMID 26972355, 2016). "In keeping with this concept, transcripts encoding IL-6 and IL-11, key cytokines involved in inflammation-associated Stat3 activation in cancer, were marginally elevated after one week of GLI2A expression but highly induced by 2 and 3 weeks, when Stat3 activation is widespread." (PMID 26859571, 2016). "In both the in vivo and in vitro experiments, signal transducer and activator of transcription 3 (STAT3) phosphorylation was decreased in the B7-H3 knockdown cell variants, whereas STAT3 phosphorylation was increased in the B7-H3-over-expressing cancer cells." (PMID 27145365, 2016). "Moreover, several anti-apoptotic proteins, such as Bcl-2 and Mcl-1, which are known to be crucial for cancer cell survival, are direct target genes of STAT3 and NFкB." (PMID 27539371, 2016). "In addition, STAT3 is persistently activated in many human cancers during cancer development and progression." (PMID 27729020, 2016). "However, presently we do not know if any relationship exists between the faster migrating isoform of U-STAT3 produced by the C-28/I2 immortalized human chondrocyte cell line and any of the truncated form(s) of U-STAT3 and p-STAT3 produced by cancer cells." (PMID 27398263, 2016).
cancer (continued). "Activation of constitutive STAT3/5 can affect to oncogenesis by protecting cancer cells from apoptosis; this implies that suppression of STAT3 activation by agents such as RES could facilitate apoptosis." (PMID 26911335, 2016). "Importantly, treatment with peptide 520 suppressed JAK2, phospho-STAT3 protein expression, and induced cancer cell death in a dose-dependent manner." (PMID 27409672, 2016). "Phosphorylated STAT3 is being observed in nearly 70 % of human cancers." (PMID 27551323, 2016). "Transcription factors STAT3 and NF-κB are aberrantly activated in many cancer cells." (PMID 27074565, 2016). "Our study suggests that STAT3 may also be a downstream target of S1P that is generated from Sphk2, which may mediate its pro-survival effect in cancer." (PMID 26956050, 2016). "Because STAT3 is known to be an important molecule involved in both M2 polarization and cancer cell proliferation, we hypothesized that ONA influenced STAT3 activation." (PMID 27404320, 2016). "Activated STAT3 may play an important role in the development of cancer and phosphorylation was the major mechanism of STAT3 activation." (PMID 27504822, 2016). "To determine whether STAT3 is involved in the apoptotic effect of MPT0B098on cancer cells, we examined STAT3 activation and expression in MPT0B098 treated OSCC cell lines." (PMID 27367272, 2016). "Importantly, STAT3 activation occurs in both cancer cells and the many immune cells that infiltrate tumors, among which myeloid-derived suppressor cells (MDSCs)." (PMID 27029037, 2016). "Apart from previous reports demonstrating that IL-11 can also activate protein kinase/extracellular signal-regulated kinase (ERK), or the phsophotidylinositol-3 kinase (PI3K) pathways, the STAT3 pathway has been identified as a main pathway activated by chemokines in cancer cells." (PMID 27922075, 2016). "In addition to cell surface markers, several pathways and molecules that control self-renewal and differentiation of cancer stem cells and normal stem cells have been identified including p-STAT3, NOTCH, C-Myc, NANOG, OCT4, SOX2 and others." (PMID 27472461, 2016). "Our group has recently reviewed the role of silibinin in cancer, and we concluded that preclinical evidence in diverse cancer types suggest that silibinin might be viewed as a natural inhibitor of signal transducer and activator of transcription 3 (STAT3)." (PMID 26959886, 2016). "STAT3 is known as a critical signaling molecule involved in cancer and inflammation." (PMID 27941650, 2016). "Activated STAT3 can directly bind to the promoter of Snail or Twist1 to induce EMT in cancer cells." (PMID 27121055, 2016). "STAT3 signalling is detected in many cancers, including GBM and may contribute to GBM pathogenesis by promoting cell proliferation and survival, immune suppression, invasion, and angiogenesis." (PMID 27083054, 2016). "Consequently, STAT3 is considered as a potential cancer therapeutic target through counteracting its hyper-expression or hyper-activation." (PMID 28008316, 2016). "The effect could be abrogated by suppressing STAT3 phosphorylation or silencing IL-11Rα expression in cancer cells." (PMID 27922075, 2016). "Recent studies have suggested a correlation among autophagic markers such as LC3B, p62, Atg5, and active STAT3 in some human cancers, among which the cancers with the higher STAT3 expression showed increased expression of autophagic markers and exhibited the worst outcome." (PMID 27474168, 2016). "Inactivation of STAT3-EMT or AKT-EMT axis has been shown to inhibit cancer cell migration." (PMID 27875549, 2016). "There was an increase in the expression of cleaved caspase 3, showing that icariside II potentiated the apoptosis of cancer cells induced by these chemotherapeutic agents with the possible mechanisms involved being inhibition of STAT3 signaling pathways as well as TLR4-MyD88-ERK signaling." (PMID 27445824, 2016).
cancer (continued). "Recent studies have suggested a correlation among autophagic markers such as LC3B, p62, Atg5, and active STAT3 in some human cancers, among which the cancers with the highest STAT3 expression showed an increased expression of autophagic markers and had the worst outcome." (PMID 27474168, 2016). "Taken together, Stat3 activation might emerge as an alternative oncogenic bypass and drive cancer cells to escape the EGFR signaling or the TKI suppression." (PMID 27419630, 2016). "Collectively, these findings supported the activation of the IL-6/STAT3 pathway and aggressive cancer stem-like phenotype in IL-6high/ESE3low tumors and suggested that these tumors could be targeted by therapy opposing this pathway." (PMID 27732936, 2016). "Many of these are oncogenic viruses, again underscoring the link between STAT3 and cancer." (PMID 27458446, 2016). "Constitutively activated STAT3 has been observed in various types of cancer cell lines and tumors." (PMID 27344974, 2016). "Our findings demonstrate that DHA is a putative STAT3 inhibitor that may represent a new and effective drug for cancer treatment and therapeutic sensitization in HNSCC patients." (PMID 26784960, 2016). "NF-κB and STAT3 are essential for inflammation-promoted cancer development." (PMID 31051015, 2016). "Thus, down-regulation of STAT3 phosphorylation strongly supported our findings that TSLP promoted the apoptosis of cancer cells." (PMID 26919238, 2016). "Since constitutive activation of the STAT3 pathway has been suggested as a critical requirement for the maintenance of cancer cell stemness, we examined the effect of BIS depletion on the STAT3 expression and nuclear translocation under sphere-forming conditions." (PMID 27145367, 2016). "The studies above show the potential of targeting STAT3 in MDSCs as an anti-cancer strategy." (PMID 27029037, 2016). "Given that inhibition of STAT3 homodimers formation diminished STAT3 activity, STAT3 may represent a potential therapeutic target for OLA1P2 in cancer chemotherapy." (PMID 26898989, 2016). "Furthermore, knockdown of either IL-6R or STAT3 enhanced the anti-cancer effects of CDDP, as determined by inhibiting the cell viability and reducing the anchorage-independent growth in soft agar." (PMID 27824145, 2016). "Others have also found an association between PRL-3 and STAT3 activation in both hematological and non-hematological cancers." (PMID 27036022, 2016). "EMT transcription factors Zeb1, Snail and Twist1 are important players in the regulation of EMT during cancer metastasis through different signaling cascades, including the Akt, Erk1/2 and signal transducer and activator of transcription 3 (STAT3) signaling pathways." (PMID 27121055, 2016). "In view of the prevalence of JAK/STAT3 hyperactivation in human cancers, and the potential role of leptin in these events, selective targeting of these proteins in cancer and cancer stem cells holds promise for significant advancement in the treatment of cancer." (PMID 27472371, 2016). "Therefore, STAT3 is an intriguing target molecule for cancer treatment by suppressing antiapoptotic Bcl-2 family gene transcription through inhibition of JAK/STAT3/Bcl-2/Bcl-xL survival pathway employing niclosamide." (PMID 26194866, 2016). "In various cancers, overexpression of p-STAT3 correlated with increased invasion and metastasis." (PMID 27793010, 2016). "Therefore, several novel small-molecule compounds have been developed to inhibit STAT3 phosphorylation, but their poor solubility and ambiguous after-effects to host preclude them from clinical trials and practical uses in cancer treatment." (PMID 26784960, 2016). "In addition to activation in cancer cells, STAT3 can be activated by viruses such as HTLV1, Hepatitis B, Hepatitis C, varicella zoster virus, SV40, Friend virus and herpesvirus saimiri." (PMID 27458446, 2016).
cancer (continued). "On the other hand, ONA also slightly inhibited STAT1 and STAT5 activation, thus suggesting that the other pathways besides STAT3 also might contribute to the anti-cancer therapeutic effects of ONA." (PMID 27404320, 2016). "Also like NF-κB, STAT3 is often constitutively activated in many human cancers, including those induced by KSHV." (PMID 27166260, 2016). "However, there is evidence that downregulation of STAT3 in cancer cells impacts on the number of MO-MDSCs, while influencing the activity of PMN-MDSCs." (PMID 27029037, 2016). "In fact, STAT3 activation in cancer cells is closely related to mitochondrial pathway." (PMID 27101310, 2016). "Thus, downregulation of STAT3 activity has been considered a promising strategy for treating inflammatory diseases and cancer." (PMID 27941650, 2016). "In addition, constitutive and persistent NF-κB activation in cancer cells is partly dependent on STAT3 status." (PMID 27729020, 2016). "Likewise, persistent activation of STAT3 and, to a lesser extent, STAT5 is implicated in survival, proliferation, and invasion in cancer." (PMID 27584613, 2016). "STAT3 is part of a pathway that is critical for facilitating leptin actions on dietary intake, weight gain, and glucose metabolism; however, elevated levels have been correlated with poor prognosis among cancer patients." (PMID 27472371, 2016). "In addition to downstream targets of NFκB, we also recovered important upstream regulators for cancer development and progression, including STAT3, MAP3K8, and TNF." (PMID 27078000, 2016). "In contrast, the luminal miRNAs targeted transcription factors that controlled EMT (ZEB1/2), and biomarkers associated with fibrosis and actin cytoskeleton (collagens), and basal cancer biology (IL6, EGFR, STAT3), all of which are suppressed in luminal cancers." (PMID 27845906, 2016). "STAT3 signaling plays an important role in cancer lymphangiogenesis and metastasis." (PMID 27145366, 2016). "On the other hand, constitutive activation of STAT3, almost never associated with mutations in STAT3, is a feature of many human cancers." (PMID 27458446, 2016). "Other than STAT-3, NF-κB also plays a vital role in development and metastasis of cancer and regulates expression of many genes including MMP-9 and FAK; hence we hypothesized that NF-κB pathway would as well be impacted by OV." (PMID 27242913, 2016). "According to the studies presented here, laricitrin may have a novel mechanism for inhibiting STAT3 activation in DCs, resulting in enhancement of anticancer immunity by restoring DC function and Th1 response in cancer niches." (PMID 27833081, 2016). "STAT3 is a cytoplasmic transcription protein factor that is activated in various cancers." (PMID 28008316, 2016). "We next examined the status of mitochondrial STAT3 in cancer cells." (PMID 28004755, 2016). "Mcl-1 and Survivin are also upregulated by STAT3 signaling and promote cancer cell survival." (PMID 31051015, 2016). "A well known STAT3 inhibitor, S3I-201 (NSC 74859), is hypothesized to block STAT3 function in cancer cells by binding the STAT3 SH2 domain and disrupt STAT3 protein complexation events." (PMID 26942696, 2016). "Nuclear IKKα could directly bind to the promoters of inflammation factors and LGR5, a stem cell marker, in turn, upregulating LGR5 expression through activation of STAT3 signaling pathway during cancer progression." (PMID 27049829, 2016). "First, most human cancers demonstrate constitutively active STAT3; yet, whether STAT3 contributes during the early stages of cell transformation was not known." (PMID 27458446, 2016). "Furthermore, anti-cancer effects can be extended via the inhibition of STAT3 and cell cycle arrest, thus impeding proliferation of cancer cells." (PMID 27775562, 2016). "Aberrant activation of STAT3 has been reported to promote cancer progression in many human cancers." (PMID 27050378, 2016).